RUBCN (rubicon autophagy regulator)
Description:
Inhibits PIK3C3 activity; under basal conditions negatively regulates PI3K complex II (PI3KC3-C2) function in autophagy. Negatively regulates endosome maturation and degradative endocytic trafficking and impairs autophagosome maturation process. Can sequester UVRAG from association with a class C Vps complex (possibly the HOPS complex) and negatively regulates Rab7 activation. Involved in regulation of pathogen-specific host defense of activated macrophages. Following bacterial infection promotes NADH oxidase activity by association with CYBA thereby affecting TLR2 signaling and probably other TLR-NOX pathways. Stabilizes the CYBA:CYBB NADPH oxidase heterodimer, increases its association with TLR2 and its phagosome trafficking to induce antimicrobial burst of ROS and production of inflammatory cytokines. Following fungal or viral infection (implicating CLEC7A (dectin-1)-mediated myeloid cell activation or RIGI-dependent sensing of RNA viruses) negatively regulates pro-inflammatory cytokine production by association with CARD9 and sequestering it from signaling complexes.
Synonyms: Rubicon; KIAA0226; rundataxin; SCAR15
Tractability: Small molecule: a structure with a bound ligand is known. PROTAC: ubiquitination databases record sites on it.
Gene: Protein-coding gene on chromosome 3 (197,668,867 to 197,749,727, reverse strand). Ensembl gene ENSG00000145016.
Subcellular location: Late endosome; Lysosome; Early endosome
Subcellular location (Human Protein Atlas): Cytosol; Vesicles; Nucleoplasm
Gene Ontology:
Molecular function: phosphatidylinositol 3-kinase inhibitor activity; protein binding; phosphatidylinositol phosphate binding
Biological process: negative regulation of autophagosome maturation; negative regulation of autophagy; negative regulation of endocytosis; negative regulation of phosphatidylinositol 3-kinase/protein kinase B signal transduction; multivesicular body sorting pathway
Cellular component: early endosome; Golgi apparatus; late endosome; lysosome
Genetic constraint (gnomAD): Loss-of-function variants: 66 observed, 105.39 expected, observed/expected ratio (o/e) 0.63, 90% interval 0.51 to 0.77. The upper end of that interval is the gene's LOEUF score, 0.77, which puts it in group 3 of 6, group 1 being the genes least tolerant of losing a copy. Missense variants: 1,042 observed, 1,233.8 expected, observed/expected ratio (o/e) 0.84, 90% interval 0.8 to 0.89. Synonymous variants: 456 observed, 486.41 expected, observed/expected ratio (o/e) 0.94, 90% interval 0.87 to 1.01.
Homologues: Orthologues: chimpanzee RUBCN (99% identical), macaque RUBCN (97% identical), dog RUBCN (93% identical), pig RUBCN (93% identical), rabbit RUBCN (91% identical), mouse Rubcn (85% identical), rat Rubcn (85% identical), guinea pig RUBCN (84% identical), Caenorhabditis elegans cup-14 (13% identical), Drosophila melanogaster Plekhm1 (11% identical). Paralogues in human: RUBCNL (24% identical), PLEKHM1 (16% identical), PLEKHM3 (13% identical), DEF8 (13% identical).
Diseases named in the same sentence as RUBCN in open-access papers:
RUBCN is named in the same sentence as 33 diseases in open-access papers, as found by Europe PMC text mining. Sharing a sentence is not in itself a finding about the gene and the disease. The quoted sentences say what the papers report.
Ataxia (5 papers, 2016 to 2023). Ataxia refers to impaired coordination of voluntary muscle movement. "Indeed, mutations in the human RUBCN gene are associated with a familial form of ataxia with impaired lysosomal degradation." (PMID 37248218, 2023).
systemic lupus erythematosus (3 papers, 2019 to 2022). An autoimmune multi-organ disease typically associated with vasculopathy and autoantibody production. "Defective clearance of apoptotic cells following LAP deficiency resulting from lack of CYBB/NOX2 or RUBCN in phagocytic cells predisposes mice to an autoimmune disease resembling systemic lupus erythematosus." (PMID 30403914, 2019).
Autoimmunity (2 papers, 2022). The occurrence of an immune reaction against the organism's own cells or tissues. "The cytosolic protein rubicon (RUBCN) has been implicated in the removal of necrotic debris and autoimmunity." (PMID 35288534, 2022).
breast carcinoma (2 papers, 2020 to 2026). "Through GSEA and other methodologies, the potential mechanisms underlying the association between RUBCN expression and breast cancer progression were explored, aiming to provide novel theoretical insights for the treatment of breast cancer." (PMID 41592105, 2026). "The Elastic_net_0.1 model identified RUBCN as a risk gene for breast cancer." (PMID 41592105, 2026). "To evaluate RUBCN expression at the protein level, we performed immunohistochemical (IHC) analysis on five paired samples of primary breast cancer and adjacent normal tissues." (PMID 41592105, 2026). "Enrichment analysis indicated that RUBCN likely promotes breast cancer progression by regulating cell cycle and invasion processes." (PMID 41592105, 2026). "Analysis of autophagy-related gene expression data identified RUBCN as a novel biomarker influencing the pathogenesis and progression of breast cancer, underscoring its potential as a therapeutic target." (PMID 41592105, 2026). "RUBCN expression was verified in breast cancer cell lines and clinical tissue specimens via Western blotting, quantitative real-time reverse transcription PCR, and immunohistochemistry." (PMID 41592105, 2026). "Knockdown of RUBCN was shown to suppress the proliferative and invasive abilities of breast cancer cells." (PMID 41592105, 2026). "Future studies should emphasize in vivo functional validation using animal models and screen for targeted agents capable of modulating RUBCN expression or activity, thereby facilitating the development of innovative therapeutic strategies for breast cancer treatment." (PMID 41592105, 2026). "Beyond well-studied genes like ATG4A, other less-characterized autophagy regulators, such as RUBCN, may also play critical roles in breast cancer pathogenesis, warranting further investigation." (PMID 41592105, 2026). "Functional assays, such as the Cell Counting Kit-8 assay, 5-ethynyl-2’-deoxyuridine incorporation assay, wound healing assay, and Transwell invasion assay, were employed to evaluate the effects of RUBCN knockdown on breast cancer cell proliferation and invasion." (PMID 41592105, 2026). "Spatial transcriptomics profiling of breast carcinoma sections revealed a significant positive correlation between RUBCN expression levels and the proportion of malignant cells within micro-regions, while showing an inverse association with stromal components, particularly immune cell infiltration." (PMID 41592105, 2026). "Together, these findings establish RUBCN as a promising therapeutic target in breast cancer." (PMID 41592105, 2026).
Nephropathy (2 papers, 2022). A nonspecific term referring to disease or damage of the kidneys. "Serum levels of RUBCN did not significantly differ between controls (G4) and diabetic patients without nephropathy (G1)." (PMID 36476132, 2022).
acute kidney injury (1 paper, 2022). Sudden and sustained deterioration of the kidney function characterized by decreased glomerular filtration rate, increased serum creatinine or oliguria. "In conclusion, these data indicate that RUBCN-deficient mice are sensitive to at least two different mouse models of acute kidney injury, and that this effect cannot be directly attributed to kidney tubules." (PMID 35288534, 2022).
autosomal recessive spinocerebellar ataxia (1 paper, 2020). "Homozygous frameshift mutation in RUBCN (Synonym: KIAA0226), known to result in endolysosomal machinery defects, has previously been reported in a single Saudi family with autosomal recessive spinocerebellar ataxia (Salih ataxia, SCAR15, OMIM # 615705)." (PMID 32450808, 2020). "Homozygous frameshift mutation in RUBCN (KIAA0226), known to result in endolysosomal machinery defects, has previously been reported in a single Saudi family with autosomal recessive spinocerebellar ataxia (Salih ataxia, SCAR15, OMIM # 615705)." (PMID 32450808, 2020).
chronic kidney disease (1 paper, 2022). Impairment of the renal function secondary to chronic kidney damage persisting for three or more months. "In addition, we find aged RUBCN-deficient male mice to develop chronic kidney disease and proteinuria." (PMID 35288534, 2022). "In addition, we identify the RUBCN-deficient mice as mildly affected by chronic kidney disease over the first year of life, but we did not detect the development of a severe autoimmune phenotype." (PMID 35288534, 2022).
Impaired glucose tolerance (1 paper, 2022). An abnormal resistance to glucose, i.e., a reduction in the ability to maintain glucose levels in the blood stream within normal limits following oral or intravenous administration of glucose. "But their experiment on RUBCN-deficient mice showed an unexpected association between RUBCN deficiency and impaired glucose tolerance as well as insulin resistance." (PMID 36476132, 2022).
ischemia reperfusion injury (1 paper, 2022). Adverse functional, metabolic, or structural changes in ischemic tissues resulting from the restoration of blood flow to the tissue (reperfusion), including swelling; hemorrhage; necrosis; and damage from free radicals. "Here, we demonstrate that RUBCN-deficient mice are hypersensitive to renal damage induced by ischemia-reperfusion injury (IRI) and cisplatin-induced AKI." (PMID 35288534, 2022). "We provide evidence for RUBCN-deficient mice to be sensitive to kidney ischemia-reperfusion injury (IRI)." (PMID 35288534, 2022).
Obesity (1 paper, 2024). Accumulation of substantial excess body fat. "Research using mouse models, specifically those with a deletion of the negative autophagy regulator RUBCN/rubicon, demonstrates that increased autophagy can lead to reduced obesity and WAT hypertrophy, when subjected to a pro-obesogenic diet." (PMID 39118171, 2024).
prostate carcinoma (1 paper, 2021). A carcinoma that arises from epithelial cells of the prostate gland. "Further multivariate Cox regression analysis was performed to select 6-gene prognostic signature (FADD, GABARAPL2, MYC, RAB24, RUBCN, and NPC1) and calculated the risk score of the prostate cancer patients." (PMID 33402116, 2021).
viral infection (1 paper, 2019). "In agreement with the role of H3K79 methylation in viral infection, alterations in RUBCN, TRIM25 and BCL3 gene expression in DOT1L down-regulated cells were found." (PMID 31727944, 2019).
infection (3 papers, 2017 to 2025). The state of being infected such as from the introduction of a foreign agent such as serum, vaccine, antigenic substance or organism. "We found that after 2 hours of infection, most bacteria colocalized with RUBCN, UVRAG, NOX2 and LC3, which clearly suggests that bacterial uptake in macrophages involves LAP." (PMID 40395986, 2025). "Indeed, we show that T. whipplei infection triggers an early blockade of autophagy which is further reinforced over time by the infection-induced overexpression of RUBCN." (PMID 40395986, 2025).
cancer (2 papers, 2025 to 2026). A tumor composed of atypical neoplastic, often pleomorphic cells that invade other tissues. "The core proteins of the LAP PI3KC3 complex (VPS34, VPS15, BECN1, UVRAG, RUBCN) present potential targets for developing novel cancer therapies." (PMID 39941753, 2025). "Immunohistochemical results confirmed upregulated RUBCN expression in carcinoma tissues." (PMID 41592105, 2026).
tumor (2 papers, 2024 to 2026). "Quantitative IHC scoring revealed that RUBCN protein levels were significantly higher in tumor tissues compared with their paired normal counterparts." (PMID 41592105, 2026). "Functional analyses revealed that knocking down RUBCN expression markedly reduced tumor cell proliferation, migration, and invasion capacities." (PMID 41592105, 2026). "These consistent spatial patterns indicate that dysregulated RUBCN expression and its biological impact within the tumor microenvironment are primarily attributable to malignant cell populations." (PMID 41592105, 2026). "Consistently, co-culture with apoptotic tumour cells promoted the expression of RUBCN in macrophages compared with M0 group." (PMID 39756316, 2024). "Furthermore, RUBCN expression gradiently decreased from the tumor core to adjacent non-tumor tissues." (PMID 41592105, 2026). "Furthermore, RUBCN expression showed a negative correlation with immune cell infiltration, suggesting its potential role in mediating tumor immune escape by suppressing immune infiltration, thereby promoting BRCA tumorigenesis." (PMID 41592105, 2026).
RUBCN also shares sentences with these, for which no sentence is quoted: autoimmune disease (2 papers); Sepsis (2); Alzheimer disease (1); breast tumors (1); diabetic kidney disease (1); Dystonia (1); heart failure (1); Insulin resistance (1); leukemia (1); lung carcinoma (1); melanoma (1); microcephaly (1); pituitary adenomas (1); pneumonia (1); prostate tumor (1); Salih ataxia (1); Stroke (1).